M6PR (mannose-6-phosphate receptor, cation dependent)
Description:
Transport of phosphorylated lysosomal enzymes from the Golgi complex and the cell surface to lysosomes. Lysosomal enzymes bearing phosphomannosyl residues bind specifically to mannose-6-phosphate receptors in the Golgi apparatus and the resulting receptor-ligand complex is transported to an acidic prelyosomal compartment where the low pH mediates the dissociation of the complex.
Synonyms: CD-MPR; MPR 46; MPR46; CD-M6PR; MPR-46; SMPR
Tractability: Antibody: its Gene Ontology location is reachable by antibodies, with high confidence; UniProt predicts a signal peptide or a membrane-spanning region. PROTAC: ubiquitination databases record sites on it; its protein half-life has been measured.
Target class: Membrane receptor
Gene: Protein-coding gene on chromosome 12 (8,940,358 to 8,951,856, reverse strand). Ensembl gene ENSG00000003056.
Subcellular location: Lysosome membrane
Pathways (Reactome):
Vesicle-mediated transport: Cargo recognition for clathrin-mediated endocytosis; Clathrin-mediated endocytosis; Lysosome Vesicle Biogenesis; Retrograde transport at the Trans-Golgi-Network
Metabolism: Glycosphingolipid catabolism
Gene Ontology:
Molecular function: cargo receptor activity; protein binding; retromer complex binding; protein domain specific binding
Biological process: Golgi to lysosome transport; glycosphingolipid catabolic process; lysosomal transport; protein targeting to lysosome
Cellular component: endosome; membrane; perinuclear region of cytoplasm; clathrin-coated endocytic vesicle membrane; late endosome; plasma membrane; trans-Golgi network; trans-Golgi network membrane; transport vesicle; cytoplasm; cytosol; endomembrane system; Golgi apparatus; lysosomal membrane
Genetic constraint (gnomAD): Loss-of-function variants: 19 observed, 33.15 expected, observed/expected ratio (o/e) 0.57, 90% interval 0.4 to 0.84. The upper end of that interval is the gene's LOEUF score, 0.84, which puts it in group 3 of 6, group 1 being the genes least tolerant of losing a copy. Missense variants: 291 observed, 351.21 expected, observed/expected ratio (o/e) 0.83, 90% interval 0.75 to 0.91. Synonymous variants: 111 observed, 130.53 expected, observed/expected ratio (o/e) 0.85, 90% interval 0.73 to 1.
Homologues: Orthologues: chimpanzee M6PR (100% identical), macaque M6PR (99% identical), rabbit M6PR (95% identical), dog M6PR (95% identical), pig M6PR (95% identical), mouse M6pr (92% identical), rat M6pr (91% identical), guinea pig M6PR (91% identical), tropical clawed frog m6pr (57% identical), zebrafish m6pr (45% identical).
Diseases named in the same sentence as M6PR in open-access papers:
M6PR is named in the same sentence as 34 diseases in open-access papers, as found by Europe PMC text mining. Sharing a sentence is not in itself a finding about the gene and the disease. The quoted sentences say what the papers report.
breast carcinoma (4 papers, 2018 to 2025). "After overexpressing M6PR in HER2-positive breast cancer cells, the number of living cells was calculated using a CCK8 kit, and the results showed that M6PR overexpression in HCC1954 and JIMT-1 increased the sensitivity of breast cancer cells to pyrotinib." (PMID 38203393, 2023). "To select suitable cell lines to construct stably transfected, overexpressed, and knockdown cells, we detected M6PR RNA in normal mammary epithelial cells and breast cancer cell lines." (PMID 38203393, 2023). "In summary, this study is the first to show that MNX1 enhances sensitivity to anti-HER2-targeted therapy in HER2-positive breast cancer by transcriptional activation of M6PR." (PMID 38203393, 2023). "M6PR has been associated with a potential anti-tumor role due to its ability to bind and degrade the mitogen insulin-like growth factor 2 (IGF2), but so far it was mentioned only in connection with breast cancer." (PMID 40649716, 2025). "By detecting the expression of M6PR in HER2-positive breast cancer cells, stably transfected M6PR overexpression and knockdown cells were constructed in HCC1954 and JIMT-1 breast cancer cells." (PMID 38203393, 2023).
melanoma (4 papers, 2014 to 2025). A malignant, usually aggressive tumor composed of atypical, neoplastic melanocytes. "As a control, we observed the M6PR in uninfected melanoma cells, where the M6PR was found mainly in the Golgi complex surrounding the nuclei (Fig. 7E1 to -3)." (PMID 32493818, 2020). "Therefore, we reasoned that any virus-M6PR interaction would be easier to detect in human melanoma cells because the viral highways are easily seen by confocal microscopy." (PMID 32493818, 2020). "Increased expression of M6PR, IGF2R, and SORT1 has been found in melanoma across different independent gene expression datasets." (PMID 41155412, 2025). "We treated human melanoma MNT-1 cells with the PI3K pathway inhibitors wortmannin and YM201636 for 24 hours, and we stained for M6PR." (PMID 25170965, 2014). "Enhanced M6PR and IGF2R may facilitate anterograde and retrograde transport between lysosomes and the trans-Golgi network in melanoma cells to maintain the composition and function of the constituent organelles." (PMID 41155412, 2025). "When human melanoma MNT-1 cells and melanocytes were treated with sucrose, we observed the decreased melanin content, the reduced merged expression of M6PR with TYRP-1 or PMEL17 and swollen vacuoles, implying that hyperosmotic stress disturbs the proper vesicle trafficking for melanosome formation." (PMID 25170965, 2014).
cervical carcinoma (3 papers, 2019 to 2020). A carcinoma arising from either the exocervical squamous epithelium or the endocervical glandular epithelium. "In contrast to IGF2R, M6PR knockdown did not influence intracellular cathepsins, protein ubiquitinylation, or cervical cancer cell survival." (PMID 31748500, 2019). "Furthermore, the mRNA expression levels of M6PR did not impact the prognosis of cervical cancer patients." (PMID 31748500, 2019). "DNA microarray analysis showed that M6PR was not aberrantly expressed in cervical cancer tissues." (PMID 31748500, 2019).
Fabry disease (2 papers, 2012 to 2021). Fabry disease (FD) is a progressive, inherited, multisystemic lysosomal storage disease characterized by specific neurological, cutaneous, renal, cardiovascular, cochleo-vestibular and cerebrovascular manifestations. "Taken together, our data provide evidence that sortilin is a new α-Gal A receptor expressed in renal endothelial cells and that this receptor together with the M6PR is able to internalize circulating α-Gal A during enzyme replacement therapy in patients with Fabry disease." (PMID 22768187, 2012). "Thus, our data indicate that circulating α-Gal A may be taken up by renal ECs by a M6PR- and sortilin- mediated pathway during ERT in Fabry disease patients." (PMID 22768187, 2012).
Listeria monocytogenes infection (2 papers, 2017 to 2022). "In the early phase of Listeria monocytogenes infection, the majority of antigen specific CTLs expressed high levels of M6PR, while CTLs that expressed low levels of M6PR survived the early phase of contraction." (PMID 35326588, 2022). "We found that nearly all antigen-specific CD8+ T cells upregulated M6PR during the early phase of Listeria monocytogenes infection, and subsequently ~25% of them downregulated M6PR at the peak." (PMID 28496990, 2017).
medulloblastoma (2 papers, 2019 to 2024). A malignant, invasive embryonal neoplasm arising from the cerebellum. "MiR-204 expression in medulloblastoma cells resulted in downregulation of both M6PR and IGF2R that mediate transport of lysosomal enzymes from the Golgi apparatus to lysosomes." (PMID 30944042, 2019). "Known validated targets of miR-204 like RAB22A, M6PR are at the top of the list whose downregulation upon miR-204 expression was further confirmed by real time RT-PCR in the three medulloblastoma cell lines." (PMID 30944042, 2019). "Transcriptome sequencing / real time RT-PCR / western blot analysis showed downregulation of RAB22A, M6PR, EZR, EPHB2, upon miR-204 expression in medulloblastoma cells as well." (PMID 30944042, 2019). "In addition, miR-204 downregulates M6PR, IGF2R genes involved in the lysosomal segregation of cathepsin B and cathepsin D lysosomal enzymes in medulloblastoma cells." (PMID 38611021, 2024).
Angelman syndrome (1 paper, 2020). A neurogenetic disorder characterized by severe intellectual deficit and distinct facial dysmorphic features. "In addition to using age-matched subjects as controls, we examined M6PR trafficking in neurons derived from DPSCs from Angelman syndrome (AS) patients, a phenotypically distinct paternally imprinted neurogenetic disorder caused by maternal deletions of the same 15q11.2-q13 chromosomal region." (PMID 32879135, 2020).
asthma (1 paper, 2015). "It was hypothesized that the identified downregulation of M6PR, TPP1, GLB1, NEU1, ACP2, LAMP1 and HGSNAT leads to disorders of lysosome function, which results in asthma by causing T-cell dysfunction." (PMID 25633562, 2015).
atopic asthma (1 paper, 2015). An asthma that is characterized by symptoms that are triggered by an allergic reaction caused by inhaled allergens such as dust mite allergen, pet dander, pollen and mold. "Among the genes identified in the present study (M6PR, TPP1, GLB1, NEU1, ACP2, LAMP1 and HGSNAT) that were significantly associated with lysosomal function, only TPP1 has been confirmed as being associated with atopic asthma." (PMID 25633562, 2015).
autism (1 paper, 2022). Persistent deficits in social interaction and communication and interaction as well as a markedly restricted repertoire of activity and interest as well as repetitive patterns of behavior. "To further clarify the mechanism by which PGRN is expressed at low levels in the VPA-induced rat model of autism, we assessed the expression of sortilin, PSAP and M6PR." (PMID 35318322, 2022).
autoimmune disease (1 paper, 2017). A disorder resulting from loss of function or tissue destruction of an organ or multiple organs, arising from humoral or cellular immune responses of the individual to their own tissue constituents. "Therefore, understanding the signals that regulate M6PR expression in T cells will have implication for modulating T-cell immunity in both infectious and autoimmune diseases." (PMID 28496990, 2017).
breast tumor (1 paper, 2021). "The inhibitory ability of M6PR has also been verified in vivo for choriocarcinoma and breast tumor cells." (PMID 34604035, 2021).
lung carcinoma (1 paper, 2021). "Our research suggested that Gimap5 could inhibit the growth of lung cancer by interacting with M6PR and that it could be a potential biomarker for the diagnosis and prognosis of lung cancer." (PMID 34604035, 2021). "Overall, our research suggested that Gimap5 could inhibit the growth of lung cancer by interacting with M6PR and that it could be a potential biomarker for the diagnosis and prognosis of lung cancer." (PMID 34604035, 2021). "This outcome suggested that Gimap5 promoted the transfer of M6PR to the cell membrane and might inhibit the growth of lung cancer cells via the processing of M6P modified ligands." (PMID 34604035, 2021). "Therefore, we believed that Gimap5 might play a role in the degradation of M6P modified ligands (i.e., PADI4) via M6PR, thereby inhibiting the growth of lung cancer." (PMID 34604035, 2021).
squamous cell carcinoma (1 paper, 2021). A carcinoma arising from squamous epithelial cells. "In one study, it was proven that M6PR could interact with matrix degradation protease to inhibit the tumorigenicity and invasiveness of squamous cell carcinoma cells." (PMID 34604035, 2021).
tumor (15 papers, 2017 to 2025). "The IGF-2R/M6PR, which is considered to act as a tumor growth suppressor, has two forms: a membrane-associated and a soluble one, both of which interact with several ligands, including IGF-2, TGFβ and lysosomal enzymes." (PMID 33946484, 2021). "Additionally, M6PR is a frequent finding in PCNSLs and is associated with the tumor immune microenvironment’s features." (PMID 34782660, 2021). "However, 3-MA caused a significant reversal in the reduction in tumor cell viability induced by combination treatment with chemotherapy and T4 cells, suggesting that exposure of M6PR to the tumor cell surface plays an essential role in synergistic killing." (PMID 30167862, 2018). "Taken together, this study presents the first proof that exosomal M6PR and EphB4 play essential roles in tumor angiogenesis and malignancy, and that serum M6PR is a novel prognostic marker for ESCC patients." (PMID 36632458, 2023). "M6PR is a receptor for granzyme B (GrzB) released by activated cytotoxic T cells, and the binding of M6PR to GrzB leads to tumor cell death." (PMID 37689699, 2023). "Nevertheless, cisplatin is capable of inducing immunogenic modulation such as the upregulation of MHC class I, M6PR, and Fas expression on tumor cells, thereby sensitizing the tumor cells to immune attack." (PMID 36497086, 2022). "More specifically, the downregulation of M6PR has been shown to increase the growth rate and tumor incidence of choriocarcinoma cells." (PMID 34604035, 2021). "Paclitaxel, cisplatin, and doxorubicin treatment rendered tumor cells more sensitive to CTL killing by upregulating mannose-6-phosphate receptors (M6PR) on the tumor cell surface, which augments cell membrane permeability to granzyme B." (PMID 34497771, 2021). "Our follow-up study also showed that the function of Gimap5 depended on its interacting protein M6PR, a tumor suppressor gene." (PMID 34604035, 2021). "Functionally, co-culturing T4 cells with tumor cells following chemotherapy resulted in an increase in intracellular tumor Granzyme B, possibly implicating M6PR as a ‘gateway’ for Granzyme B to enter the tumor." (PMID 30167862, 2018). "We showed that M6PR is upregulated on the tumor cell surface following chemotherapy treatment in vitro, both by flow cytometry and immunofluorescence." (PMID 30167862, 2018). "It has been suggested in the literature that chemotherapy induces an upregulation in tumor cell surface M6PR, facilitating cytotoxic killing by T cells." (PMID 30167862, 2018). "And the function of M6PR in tumor metastasis and TME is largely unclear." (PMID 36609569, 2023). "Moreover, in vitro assays and BALB/c mouse tumor models revealed that miR-6750 directly targeted mannose 6-phosphate receptor (M6PR)." (PMID 36609569, 2023). "Furthermore, select immunogenic modulators also upregulate mannose-6-phosphate receptors (M6PR) on the tumor cell surface, which augment cell membrane permeability to granzyme B produced by activated NK cells and CTLs." (PMID 36497086, 2022). "Therefore, the inactivation of the M6PR gene is highly correlated with the tumor, and this gene acts as a tumor suppressor or inhibits tumor growth." (PMID 34604035, 2021). "Previous research suggested that the anti-proliferative activity of M6PR in tumor cells could be traced to its influence on IGF-II signal." (PMID 34604035, 2021). "It has been shown that M6PR acts as a link between autophagy, chemotherapy and immunotherapy, since autophagy controls its traffic between the cytoplasm and the cell surface, where it augments T cell cytotoxic activity against tumor cells." (PMID 33946484, 2021). "Therefore, we next examined the level of M6PR, both in cell lines and xenograft tumor tissues." (PMID 36674931, 2023). "As expected, the addition of 3-MA to chemotherapy resulted in a downregulation of tumor cell surface M6PR; mRNA levels did not change." (PMID 30167862, 2018).
tumor (continued). "Tumor mRNA levels of M6PR did not change which, together with our immunofluorescence and flow cytometry findings, contribute to the hypothesis of a chemotherapy-induced shuttling of M6PR rather than increased de novo synthesis." (PMID 30167862, 2018). "In addition, paclitaxel, cisplatin, doxorubicin could upregulate the expression of mannose-6-phosphate receptor (M6PR) on the surface of tumor cells, thereby increasing the permeability of cell membrane to granzyme B, making the cytotoxicity of lymphocytes to tumor cells independent of perforin." (PMID 30519541, 2018).
cancer (7 papers, 2017 to 2023). A tumor composed of atypical neoplastic, often pleomorphic cells that invade other tissues. "Data from TCGA and GTEx showed that a variety of human cancers expressed a higher level of M6PR mRNA." (PMID 36632458, 2023). "M6PR overexpression was also discovered to reduce cancer cell growth in vitro and in vivo." (PMID 34604035, 2021). "In conclusion, the findings in this study demonstrated that exosomes from SRGN-overexpressing ESCC cells play important roles in cancer progression, with SRGN- induced exosomal M6PR and EphB4 having pro-angiogenic and pro-invasive functions, respectively." (PMID 36632458, 2023).
infection (2 papers, 2017 to 2022). The state of being infected such as from the introduction of a foreign agent such as serum, vaccine, antigenic substance or organism. "Instead, EV71 was efficiently uncoated 30 min after infection in late endosomes (LEs) containing hSCARB2, mannose-6-phosphate receptor (M6PR), RAB9, bis(monoacylglycero)phosphate and lysosomal associated membrane protein 2 (LAMP2)." (PMID 35929543, 2022). "We next examined the possibility of drug-mediated regulation of KIF13A and KIF13A-motorized M6PR during infection." (PMID 28496990, 2017). "In agreement with our previous study, we also demonstrate concurrent upregulation of M6PR on T cells after the infection." (PMID 28496990, 2017).
skeletal disease (1 paper, 2015). "Although ERTs have been highly beneficial to patients with these diseases, the ineffective correction of neurological, ocular and skeletal disease manifestations remains a major drawback of current therapies dependent upon MMR- and M6PR-dependent delivery." (PMID 26382970, 2015).
M6PR also shares sentences with these, for which no sentence is quoted: hepatocellular carcinoma (2 papers); lysosomal storage disease (2); chordoma (1); esophageal cancer (1); Gingival bleeding (1); lentivirus infection (1); lymphoma (1); lysosome disease (1); neuroblastoma (1); neurodegenerative disease (1); neurologic disease (1); Obesity (1); ovarian carcinoma (1); ovarian tumor (1); Parkinson disease (1); spinocerebellar ataxia (1).